TRPV1 (transient receptor potential cation channel subfamily V member 1)
Diseases named in the same sentence as TRPV1 in open-access papers (continued):
Sharing a sentence is not in itself a finding about the gene and the disease.
Arthritis (continued). "The increased levels of extra-physiologically activated TRPV1 and TRPV4 channels caused by incubation with TNF-α can significantly contribute to the activation of synoviocytes observed in joint inflammation." (PMID 19695100, 2009). "Therefore, based on such characteristics and involvement in arthritis pain, TRPV1 is considered a potential target for the treatment of arthritis." (PMID 37994506, 2024). "Somatostatin exerts both anti‐inflammatory and analgesic effects in arthritis, suggesting that the analgesic effect induced by TRPV1 agonists may be partially attributed to somatostatin released from primary afferent nerves." (PMID 37994506, 2024). "Consequently, targeting the TRPV1 channels holds significant promise as a therapeutic approach for arthritis treatment and the management of arthritic pain." (PMID 37994506, 2024). "Consequently, unravelling the link between TRPV1 and angiogenesis or lymphangiogenesis in arthritis holds significant implications for comprehending the pharmacological mechanisms of TRPV1 and identifying novel therapeutic targets for arthritis." (PMID 37994506, 2024). "TRPV1 agonists and antagonists are currently used in the treatment of arthritis pain." (PMID 37994506, 2024). "Here, we summarize the current TRPV1 channel drugs mainly used for arthritis treatment." (PMID 37994506, 2024). "Many clinical trials are also being conducted to treat arthritis and pain by targeting TRPV1." (PMID 37744324, 2023). "The development of TRPV1-targeted drugs for arthritis is actively pursued worldwide." (PMID 37744324, 2023). "Indeed, it was shown that, in a collagen-induced arthritis model, the activation of TRPV1 channels with capsaicin led to the apoptosis of synovial cells through the upregulation of [Ca2+]i, ROS and mitochondrial membrane depolarization." (PMID 36291594, 2022). "Several proton-sensing receptors, including transient receptor potential/vanilloid receptor subtype 1 (TRPV1), acid-sensing ion channel 3 (ASIC3), and proton-sensing G-protein-coupled receptors, were found to be associated with arthritis or arthritis-associated pain." (PMID 35408888, 2022). "Furthermore, mice with proteoglycan and CFA-induced arthritis were treated with guanethidine (to deplete postganglionic sympathetic terminals) or capsaicin (to destroy TRPV1+ sensory terminals) had reduced pain behavior, edema, and arthritis severity." (PMID 36387416, 2022). "TRPV1 may contribute to the pain hypersensitivity and inflammation of arthritis via an ERK-mediated pathway." (PMID 34471470, 2021). "Finally, application of TRPV1 agonists and some blockers with pronounced ability to reduce pain and joint inflammation also indicates the important role of TRPV1 in arthritis." (PMID 33477357, 2021). "However, in the arthritis model, whose pathogenesis is similar to the vertebral endplate degeneration model, the fact that TRPV1 is important in mediating hypersensitivity has been proven." (PMID 34471470, 2021). "However, in other inflammatory diseases, such as airway inflammation and arthritis, TRPV1 has been proven to exert beneficial effects via SST." (PMID 31189399, 2019). "The findings from this study using fMRI combined with an immunohistochemical/western blotting approach may provide additional insights into the functional role of TRPV1 in the normal brain, as well as the gouty arthritis scenario." (PMID 31451732, 2019). "Activation of TRPV1 enhanced mRNA level and protein level of IL-6 in FLS from RA and OA patient and application of TRPV1 antagonist could be therapeutic strategy to modulate nociception from arthritis." (PMID 31480869, 2019). "Additionally, a number of studies have demonstrated that treatment with TRPV1 agonists such as capsaicin or resiniferatoxin prior to arthritis induction leads to reduced pain and joint damage in arthritis models." (PMID 30326593, 2018).
Arthritis (continued). "Another study observed significantly reduced destruction of articular tissues in TRPV1 knockout animals in an adjuvant arthritis model, although an earlier study utilizing the same model found that wild-type and knockout animals had similar levels of joint destruction." (PMID 30326593, 2018). "Thus, the activation of TRPV1 largely appears to serve as part of a positive feedback mechanism that works to enhance the disease process and pain of arthritis." (PMID 30326593, 2018). "Depletion of TRPV1 may have reduced arthritis-induced chronic pain in the late phase (after 8 weeks)." (PMID 28827659, 2017). "TDAG8, ASIC3, and TRPV1 influence arthritis scores and RA-induced hyperalgesia." (PMID 28827659, 2017). "Genetic and pharmacological inhibition of TRPV1 can reduce arthritis-like symptoms." (PMID 27854251, 2016). "Interestingly, this effect was mediated by TRPV1 located on sensory neurons, emphasizing the neuronal component of arthritis." (PMID 26343051, 2015). "It is clear from the studies that TRPV1 at least plays a paradoxical role in inflammation in vivo, for example, exacerbating inflammation in arthritis and yet in experimentally induced sepsis, TRPV1 null mice demonstrate elevated levels of pathological markers in comparison with wild type mice." (PMID 23800232, 2013). "Current evidence for the role of TRPV1 in arthritis models is somewhat conflicting." (PMID 24280677, 2012). "In a model of rat knee joint-induced arthritis, peripheral TRPV1 and centrally increased oxidative stress can enhance pro-inflammatory cytokines production, suggesting that these inflammatory molecules can also contribute to the effect of capsaicin on B1R expression." (PMID 22264228, 2012). "Thus, the data support the benefits of agents limiting or eliminating the increases in TRPV1 mediated ROS as a novel adjuvant therapy for more comprehensive treatment of the persistent pathologic pain and inflammation of arthritis." (PMID 20691059, 2010). "Furthermore, employing TRPV1‐RNAi as a potential therapeutic approach could effectively target the TRPV1 receptor to address pathological alterations in arthritis and preserve essential physiological defence mechanisms." (PMID 37994506, 2024). "Additionally, TRPV1 channels play a vital role in nerve sensitization, defunctionalization or central sensitization, and they can release various neuropeptides that contribute to arthritis development." (PMID 37994506, 2024). "However, the role of TRPV1 in arthritis pain is also controversial." (PMID 37994506, 2024). "Future studies may be aiming at investigation how TRPV1 expression in osteoclasts can be exploited to restore the balance between osteoclast and osteoblast bone homeostasis under pathological conditions of arthritis." (PMID 37994506, 2024). "MiR‐375 and miR‐455 were identified to repress TRPV1 expression via targeting the 3’‐UTR of TRPV1 mRNA, which has been shown to be downregulated in patients with low back pain with neuropathic pain, so they may also function as therapeutic targets to indirectly modulate TRPV1 activity in arthritis." (PMID 37994506, 2024). "On the other hand, pro-inflammatory mediators and ROS activate TRPV1, promote transportation and insertion of TRPV1 from the subcellular vesicles pool, and upregulate TRPV1 expression, indicating that TRPV1 is involved in positive feedback signaling in the process of joint inflammation." (PMID 33477357, 2021). "Indeed, this TRPV1 agonist-induced analgesia has been observed in humans, as topical capsaicin application has long been used by some patients as a treatment for arthritis pain, and a review on this topic identified a number-needed-to-treat of only 3.3 for a 50% reduction in pain." (PMID 30326593, 2018). "In addition to mediating arthritic pain, a wide body of evidence suggests that TRPV1 may also play a role in facilitating the joint destruction and edema that is characteristic of arthritis." (PMID 30326593, 2018).
Arthritis (continued). "Compared to TRPV1+/+ animals, TRPV1-/- animals exhibited reduced pain and reduced joint inflammation following complete Freund’s adjuvant (CFA)-mediated induction of arthritis." (PMID 37744324, 2023). "In the present study, we demonstrate, for the first time, that TRPV1+ and TRPA1+ DRG nociceptive neurons are activated in TiO2-induced arthritis." (PMID 36677929, 2023). "TRPV1 is the most well-studied of the TRP channel family members, and this also holds true in the context of arthritis research." (PMID 30326593, 2018). "TRPV1+/+ and TRPV1+/− mice, like wild-type ICR mice, showed long-term inflammation: the mean arthritis scores increased with time and peaked at 4 weeks." (PMID 28827659, 2017). "No reduction in guarding behavior in a CFA-induced arthritis model was found after the oral administration of the TRPV1 antagonist AZD1386." (PMID 33477357, 2021). "Consistent with a decrease in arthritis scores, pannus, bone destruction, and cartilage damage were significantly reduced in TRPV1-/- mice at 4, 8, 12 weeks; was not reduced in TRPV1+/- mice at 4 weeks." (PMID 28827659, 2017). "In a rat model of adjuvant-induced arthritis in the tibial-tarsal joint, IA BoNT/A improved mechanical and thermal hyperalgesia and reduced the number of dorsal root ganglion (DRG) cells doubly positive for TRPV1 and CGRP, indicating reduced TRPV1 expression in the DRG." (PMID 32397671, 2020). "Therefore, inhibition of only TRPV1 or TRPA1 could be not enough for efficient alleviation of arthritis pain." (PMID 38132938, 2023). "None of the mode-selective TRPV1 antagonists have been tested in models of CFA- and MIA-induced arthritis." (PMID 33477357, 2021). "Unlike TRPV1, TRPV2 has been identified as a suppressor of arthritis inflammation." (PMID 36291594, 2022). "Moreover, no edema or hypersensitivity were observed in Trpv1−/− mice following joint inflammation, strengthening the assertion that TRPV1 is critically involved in the pathogenesis of arthritis-like inflammatory conditions." (PMID 27854251, 2016).
neuropathy (49 papers, 2005 to 2026). A disorder affecting the nervous system that manifests with pain, tingling, numbness, and/or muscle weakness. "The GG-genotype (rs879207, A > G) of TRPV1, a gene expressed in peripheral sensory neurons, was observed in 11.3% (n = 36) of the patients and associated with an increased risk of severe neuropathy (OR 5.2, 95%CI 2.1–12.8, adjusted p-value 0.012)." (PMID 36672910, 2023). "The present study demonstrates that NSCLC patients with the GG-genotype (rs879207) of TRPV1 are at a nearly 5-fold higher risk of developing severe neuropathy when treated with platinum-based therapy." (PMID 36672910, 2023). "We conclude that long-term TRPV1 sensitization contributes to the development of bortezomib-induced neuropathy and the consequent loss of sensation, major deficits experienced by patients under this chemotherapeutic agent." (PMID 38052846, 2023). "This study shows that patients with the GG-genotype (rs879207) of TRPV1 have an almost 5-fold higher risk of developing severe neuropathy when treated with platinum-based therapy." (PMID 36672910, 2023). "Contrarily, during the chronic stages of RTX neuropathy, TRPV1 depletion associated with neuronal injury triggered the dysfunction of PAP-mediated antinociception, consequently inducing pain transduction." (PMID 30578250, 2019). "Since pro-inflammatory cytokines are involved in the induction of B1R and that TRPV1 is associated with pain neuropathy, this series of experiments was carried out to measure their expression in STZ-diabetic rats." (PMID 20587056, 2010). "After multiple testing correction, the GG-genotype (rs879207, A > G) of TRPV1, a gene expressed in peripheral sensory neurons observed in 11.3% of the patients, was found to be associated with an increased risk of severe neuropathy (OR 5.2, 95%CI 2.1–12.8, FDR adjusted p-value 0.012)." (PMID 36672910, 2023). "Notably, FLOT1 and FLOT2 were markedly depleted in RTX neuropathy associated with TRPV1(+) neuronal depletion." (PMID 30578250, 2019). "Diosmetin has therapeutic potential for treating pain in patients with neuropathy, and the TRPV1 channel plays a crucial role in cisplatin-induced peripheral neuropathy." (PMID 41876939, 2026). "According to the studies, CCL3 can induce neuropathy by sensitization of TRPV1, P2X7R, or heterologous desensitization of the opioid receptors." (PMID 41153795, 2025). "TRPV1 has been extensively studied in the field of neuropathy and has also been shown to be dysfunctional as an ion channel in experimental models of diabetic neuropathy." (PMID 39337455, 2024). "Due to the strong sensitization of TRPV1 by all three proteasome inhibitors in the screen, as well as the high incidence of neuropathy in bortezomib-treated patients, we tested if this drug has a similar effect." (PMID 38052846, 2023). "Here,we report for the first time a series of compoundspotentiallyuseful for the management of oxaliplatin-induced neuropathy (OINP)able to modulate the human Carbonic Anhydrases (hCAs) as well as theTransient Receptor Potential Vanilloid 1 (TRPV1)." (PMID 36626645, 2023). "Paclitaxel sensitizes and activates TRPV1 function, and TRPV1 antagonists exert analgesic effects in chemotherapy-induced neuropathy." (PMID 38137890, 2023). "Topical capsaicin application can be utilized to evaluate a possible neuropathy or sensitization/overexpression of TRPV1 channels in RA patients or similar inflammatory diseases." (PMID 35499773, 2022). "In particular, some studies reported that naringin was effective for osteoarthritis pain and back pain and that the antagonist of TRPV1 was effective for osteoarthritis pain or neuropathy pain." (PMID 35052566, 2021). "Recent studies have described that TRPV1 activation is essential for establishing inflammation and neuropathy pain models, showing that the expression of this receptor is increased, which contributes to enhanced thermal sensitivity." (PMID 31947713, 2020).
neuropathy (continued). "Recent studies have reported that TRPV1 activation is essential for establishing of inflammation in the neuropathy pain models, showing that the expression of this receptor is increased, and contributing to enhanced thermal sensitivity." (PMID 31947713, 2020). "By contrast, another in vivo study showed that pharmacological antagonism of TRPV1 accelerated neuropathy of ganglion cells in rats suffering elevated intraocular pressure." (PMID 31547874, 2019). "Various models of neuropathy have shown that TRPV1 expression in nociceptors is altered under pathological conditions." (PMID 30065629, 2018). "TRPV1 expression in nociceptors is altered in different models of neuropathy under pathological conditions." (PMID 30065629, 2018). "First it has been shown that G2A activation in peripheral sensory neurons allows sensitization of the ion channel transient receptor potential V1 (TRPV1) by G2A contributing to chemotherapy-induced painful neuropathies." (PMID 30327654, 2018). "The effect of Goshajinkigan on neuropathy through inhibition or stimulation of TRPA1, TRPM8, and TRPV1 channels in oxaliplatin-induced neuropathy rat model was recently investigated." (PMID 29326595, 2017). "In particular, diabetic or other kind of neuropathies result in a decrease in TRPV1 expressing sensory neurons, mediating vasodilation." (PMID 24250792, 2013). "With RTX-induced neuropathy, thermal hypoalgesia occurred at RTXd7, corresponding to depletion of TRPV1(+) and SP(+) DRG neurons and their peripheral terminals in the skin." (PMID 23209829, 2012). "These cell culture models provide a platform for investigating mechanisms of painful neuropathies mediated by nociceptors expressing the pain sensing gene TRPV1, and its regulation by the PKC isoform PKCβII." (PMID 27721335, 2011). "Several lines of evidence ranging from in vitro and in vivo studies in animals to humans have proved TRPV1 to be a potential target in nociceptors for the treatment of pathological pain, ranging from inflammation to neuropathies." (PMID 19305786, 2008). "It is now generally accepted that the alteration of TRPV1 can be a major driver of neuropathy." (PMID 41153795, 2025). "Alteration of TRPV1 expression is reported in different models of neuropathy." (PMID 40540176, 2025). "The sensitization of TRPV1 (transient receptor potential vanilloid 1) and TRPA1 (transient receptor potential ankyrin) channels, driven by PKCε activation, has been linked to paclitaxel-induced neuropathy, manifesting as cold and mechanical allodynia." (PMID 39598298, 2024). "Increased TRPV1 expression in the dorsal horn of the spinal cord has been studied in various types of pain, such as paclitaxel-induced pain (4 mg/kg), sciatic nerve injury, and diabetes-induced neuropathy." (PMID 38137890, 2023). "Next, we tested if TRPV1 is involved in bortezomib-induced neuropathy in vivo." (PMID 38052846, 2023). "TRPV1 activation is closely related to what chemotherapy-induced neuropathy patients experience." (PMID 38137890, 2023). "•TRPV1 expression in myelinated neurons of the DRG was involved in neuropathy." (PMID 35199097, 2022). "Notably, TRPV1 is a target for treating some forms of neuropathy, and chronic TRPV1 activation can induce axon terminal ablation." (PMID 35370552, 2022). "We also hypothesized that the development of IGT neuropathy may involve a switch in TRPV1 expression from small, unmyelinated neurons to large, myelinated neurons in the DRG." (PMID 35199097, 2022). "Thus, with the study setup described in this paper, TRPV1 sensitization and neuropathy development regarding the effect of capsaicin cream on their HPTs/MPTs and ERP images can be evaluated by comparing RA patients with a HS group." (PMID 35499773, 2022). "The change in TRPV1 expression or the extent of a neuropathy development may show the ability of medications to suppress chronic inflammation and pain." (PMID 35499773, 2022).